MTA1 (metastasis associated 1)
Diseases named in the same sentence as MTA1 in open-access papers (continued):
Sharing a sentence is not in itself a finding about the gene and the disease.
cancer (continued). "At the cellular level, MTA1 overexpression in cancer cells regulates a variety of pathways that contribute to the processes leading to invasion, epithelial-to-mesenchymal transition, survival, and metastasis." (PMID 28393842, 2017). "The opposite effects were observed in MTA1-silenced cancer cells, which was consistent with previous studies." (PMID 28418915, 2017). "Once again, we found a remarkable reverse relationship between MTA1 upregulation and DNMT3a downregulation in most cancer types with a low degree of exception to this relationship." (PMID 28393842, 2017). "To explore the nature of relationship between the status of MTA1 and DNMT3a in human cancer, we first interrogated the available breast and colon microarray public datasets for the levels of DNMT3a and MTA1." (PMID 28393842, 2017). "Despite a recognized role of DNA methyltransferase 3a (DNMT3a) in human cancer, the nature of its upstream regulator(s) and relationship with the master chromatin remodeling factor MTA1, continues to be poorly understood." (PMID 28393842, 2017). "MTA1 reportedly promotes cancer cell invasion and metastasis through E-cadherin expression regulation and EMT." (PMID 28418915, 2017). "To understand the physiological relevance of MTA1 stimulation of IGFBP3 expression in cancer, we examined the status of MTA1 and IGFBP3 in context of DNMT3a expression in human tumors." (PMID 28393842, 2017). "Next, we examined the status of MTA1 and DNMT3a in 877 cases from the Cancer Cell Line Encyclopedia using cBioPortal database." (PMID 28393842, 2017). "Because of the significant clinical implications of the noted inverse MTA1-DNMT3a relationship, we next investigated the mechanism of MTA1 regulation of DNMT3a expression in cancer cells." (PMID 28393842, 2017). "We found that MTA1 immunoreactivity in malignant tumors was significantly higher than PA and higher in PA than in the normal salivary gland tissues (nSGTs)." (PMID 26878004, 2016). "Mechanistically, we demonstrated that aberrant overexpression of MTA1 resulted in activation of MTA1-dependent transcriptional signatures that promote proliferation, inflammation, invasion and survival of cancer cells." (PMID 26943043, 2016). "Some authors have shown that MTA1 overexpression is accompanied by poor prognosis in malignant tumors, with the enhancement of invasion and metastasis." (PMID 26878004, 2016). "MTA1 expression in the malignant tumors was significantly higher than that in pleomorphic adenoma (P<0.001), and higher in pleomorphic adenoma than the normal salivary glands(P< 0.001)." (PMID 26878004, 2016). "MTA1 expression in the malignant tumors was significantly higher than that in PA (P<0.001), and it was higher in PA than in the normal salivary glands (P<0.001)." (PMID 26878004, 2016). "Our findings highlight MTA1 as a key upstream regulator of prostate tumorigenesis and cancer progression." (PMID 26943043, 2016). "MTA1 had been shown to be overexpressed in malignant tumors with the enhancement of invasion and metastasis." (PMID 26878004, 2016). "Previous studies have shown that eIF5A2 eliminates the augmentation of carcinoma cell migration, invasion, and the EMT through down-regulating MTA1 (metastasis-associated 1)." (PMID 27028999, 2016). "It has been reported that MTA1 regulates cancer behaviors through the Wnt pathway, which is a key knot in the stemness regulation network." (PMID 25644400, 2015). "In cancer, MTA1 levels are significantly upregulated compared to adjacent normal prostate tissue and PIN." (PMID 25797255, 2015). "Multiple groups have demonstrated that RNAi of YB-1 and MTA1 in vitro leads to a significant decrease in the invasive capacity of cancer cells." (PMID 25797255, 2015). "A significant difference was also proved for MTA1 overexpression in cancers of various histopathological subtypes (p = 0.03)." (PMID 26698569, 2015).
cancer (continued). "Some studies have indicated that down-regulation of MTA1 by RNAi leads to an increase expression of E-cadherin which acts as a key role in epithelial-to-mesenchymal transition in cancer cells." (PMID 26689197, 2015). "Many studies have explored the expression levels of MTA family members, especially MTA1, in human cancers." (PMID 26503703, 2015). "The force driving cancer metastasis is stress, and the struggle for existence and MTA1 overexpression is a sign of these stresses." (PMID 25332145, 2014). "We observed the general expression of MTA1 in virtually all tissues and cell lines, regardless of normal or cancerous or adult or embryonic, suggesting an important physiological role for MTA1, in addition to its well-known roles in cancer." (PMID 24970816, 2014). "Theses results not only suggest that nuclear MTA1 is a good marker for cancer differentiation diagnosis and a potential target for the treatment of cancers but also reveal the necessity to differentially examine the functions of nuclear and cytoplasmic MTA1." (PMID 24970816, 2014). "Concerning the molecular mechanism of MTA1 in cancer cell metastasis, MTA1 has been reported to be involved in cancer development in several ways." (PMID 24396455, 2014). "Both carcinogenesis and cancer metastasis are rather complex issues, though, and so is MTA1’s role in these processes." (PMID 25332145, 2014). "Since HIF1a plays an important role in angiogenesis and promotion of cancer metastasis, MTA1 also has a part to play in both the normal wound healing and cancer." (PMID 25332145, 2014). "In the cellular biological studies, a causal correlation between MTA1 expression and the in vitro migration and invasion ability of LSCC cancer cells was identified." (PMID 24396455, 2014). "MTA1 was first isolated from a metastatic breast cancer cell line and has since been shown to be upregulated in several other metastatic human cancers." (PMID 25352341, 2014). "The percentage of HDAC1- and MTA1-positive expression in low-grade dysplasia of BM was as high as that of cancer." (PMID 25009653, 2014). "MTA1 is one that attracts widespread attention for its close relationship with cancer progression, metastasis, and its fantastic role in many other cellular processes." (PMID 25332145, 2014). "Metastasis is a cancer cell stress response, and MTA1 as a stress protein is a stress level indicator." (PMID 25332145, 2014). "The MTA family proteins, especially MTA1, have been shown to play important roles in diverse processes including transcriptional regulation, DNA damage repair and cancer." (PMID 23286669, 2013). "All family members of metastasis tumor antigen (MTA) proteins including MTA1, MTA2, MTA3 and MTA1s have been closely linked to cancer progression and metastasis." (PMID 23671646, 2013). "As an important regulator of cell fate with a role in the oncogenesis and progression of many malignant tumors, MTA1 has attracted widespread attention." (PMID 23227138, 2012). "The transcription activator function of MTA1 is evident from reports showing the stimulation of breast cancer-amplified sequence 3 (BCAS3) and paired box gene 5 (Pax 5) promoters mainly through the interaction with RNA polymerase II." (PMID 21364872, 2011).
cancer (continued). "Actually, depletion of MTA1 can result in a defect of G2/M checkpoint in human cancer cells on the premise of UV radiation." (PMID 22022494, 2011). "MTA1 is expressed in numerous human cancers, including breast, prostate and gastro-intestinal cancers and its expression correlates with tumor aggressiveness and metastasis." (PMID 24212658, 2011). "Subsequent studies found MTA1 to be widely up-regulated in various human cancers and established to be involved in tumorigenesis, tumor invasion, and metastasis." (PMID 21364872, 2011). "Despite its strong correlation with the metastatic potential of cancer cells, MTA1 can also regulate crucial cellular pathways by modifying the acetylation status." (PMID 21082030, 2010). "And finally, MTA1 which was found to represent the most promising gene based on previously published literature reporting on its overexpression in various cancers." (PMID 18949081, 2008). "MTA1 transcripts were observed to be over-expressed in normal human testes as well as various cancer tissues when compared to the panel of normal tissues." (PMID 18949081, 2008). "Enhanced expression of MTA1 mRNA was also found in a variety of other human cancerous tissues and carcinoma cell lines, for example in colorectal, gastric, or oesophageal carcinomas and thymoma." (PMID 14735193, 2004). "However, MTA1 immunoreactivity was found to be significantly higher in malignant tumors compared to benign tumors, as well as higher in benign tumors compared to normal salivary gland tissues (nSGTs)." (PMID 40660330, 2025). "The role of MTA1 in cancer cell EMT-related events has been shown previously." (PMID 40351767, 2025). "So, MTA1 reportedly promotes cancer cell invasion and metastasis through EMT." (PMID 40660330, 2025). "MTA1, a core member of the MTA family, is upregulated in numerous cancers and is associated with EMT, invasion, metastasis, angiogenesis, resistance to therapy, and poor prognosis in patients with cancer." (PMID 40565190, 2025). "As the diverse functions of MTA1 and its role in various cancers have been discussed continuously." (PMID 41159000, 2025). "As regards the pathological variables, there were high statistically significant differences in MTA1 expression considering the following variables: the histological type (P = 0.005) and grade of carcinoma (P = 0.001), and the incidence of lymph vascular invasion (P = 0.000)." (PMID 40660330, 2025). "Modulation of FAK, VEGF R1, and MTA1 by phytobioactives may hold promise for slowing the progression of cancer." (PMID 39355129, 2024). "Additionally, MTA1 is also involved in regulating the expression of matrix metalloproteinases (MMPs), which are enzymes that facilitate cancer cell invasion and migration by degrading the extracellular matrix." (PMID 39355129, 2024). "The modulatory effect of MTA1 on mitochondrial glucose metabolism may indicate its value for cancer treatment." (PMID 37442756, 2023). "Studies have reported that MTA1 overexpression enhances cancer cell migration." (PMID 37892177, 2023). "However, MTA1 and HDACs of the NuRD complex represent potential therapeutic targets for cancer chemoprevention." (PMID 37509346, 2023). "We hypothesized that the enriched CD8+ T cells were functionally impaired or that cancer cells expressing high levels of MTA1 may be intrinsically resistant to the killing effects of CD8+ T cells." (PMID 35350571, 2022). "Our report guarantees further study on whether MTA1 can serve as a marker for the sensitivity of cancers to immunotherapy or even as an immunotherapy target in combination with current immune checkpoint blockers." (PMID 35350571, 2022).
cancer (continued). "Not surprisingly, miRNAs that are linked to MTA1 affect cancer progression and the metastatic potential of cells." (PMID 36091792, 2022). "Additionally, the metastatic tumor antigen 1 (MTA1), a cancer-promoting molecule, was introduced as an example to address the importance of a suitable animal model for studying HBV-related hepatocarcinogenesis." (PMID 34502289, 2021). "In line with this, it has also been suggested recently that H1.2T146 phosphorylation mediated by DNA-PK can promote binding to Metastasis-associated 1 (MTA1, which shows over-expression within some human cancers) and inhibits pre-metastasis, MTA1-mediated cell proliferation, and invasion." (PMID 35087830, 2021). "The dysregulation of above AS events in ATRX and MYBL2 are significantly related to mitosis and tumorigenesis in cancer patients, suggesting that MTA1 may regulate mitosis and tumorigenesis by targeting the AS of these two mitosis regulators." (PMID 32901005, 2020). "Indeed, the MTA1-overexpressed cancer cells formed more cancer stem cell spheres in vitro and initiated more tumors in mice." (PMID 32901005, 2020). "MTA1 has been reported to promote cancer cell invasion by depressing the E-cadherin expression." (PMID 33059651, 2020). "MTA1 has been shown to be overexpressed in various cancers, including breast cancer, pancreatic cancer, and ovarian cancer, and its overexpression correlates with cancer progression and poor outcome in many cancer types." (PMID 32070428, 2020). "Despite these documented roles, specifically how MTA1 induces metastasis in cancer is unclear." (PMID 30782165, 2019). "Using a cancer biomarker antibody array, we identified MTA1 protein in BC exosomes that may regulate hypoxia and estrogen signaling and contribute to BC progression." (PMID 30782165, 2019). "MTA1 protein interacts with histone deacetylase to form a nucleosome remodeling histone deacetylase (NuRD) complex, which has been shown to regulate oncogenesis, angiogenesis, and cancer progression of a variety of cancers." (PMID 31281798, 2019). "Some studies reported a relationship between metastasis-associated protein 1 (MTA1) and the regulation of Wnt1 in endothelial and cancer cells, and MTA1 might be a novel target for leptin." (PMID 31736756, 2019). "It appeared that MTA1 regulated DcR3 expression in SAS cancer cells." (PMID 30537218, 2019). "We report herein that Gnetin C, a resveratrol dimer and dietary compound found in the melinjo plant, is more potent than resveratrol and pterostilbene in exerting its anticancer activity in PCa, at least in part, through the inhibition of cancer-promoting co-operation between MTA1 and ETS2." (PMID 31487842, 2019). "Future studies shall explore whether IL-17 promotes cancer metastasis through upregulation of MTA1 expression." (PMID 31281798, 2019). "However, inhibitors that disrupt MTA1 interactions with crucial binding partners, such as histone deacetylase 1 (HDAC-1), have been shown to reduce metastasis and MTA1 expression in cancer cell lines and animal models." (PMID 30782165, 2019). "Overexpression of MTA1 has been reported in various cancers." (PMID 30027683, 2018). "Overall, results presented here show that the high levels of IGFBP3, low levels of DNMT3a, and high levels of MTA1 may result in poor prognosis of cancer patients and that the expression of IGFBP3 by MTA1 could be regulated by direct or indirect mechanisms." (PMID 28393842, 2017). "MTA1 reportedly contributes to tumor metastasis by promoting EMT in some cancers." (PMID 28418915, 2017). "Here we investigated the role of MTA1 in the regulation of DNMT3a expression in cancer cells." (PMID 28393842, 2017). "The combinatorial approach may be a viable tool for management of cancer progression in certain subpopulation of PCa patients with high levels of MTA1." (PMID 29024573, 2017). "MTA1 is a critical regulator of the metastatic process in various types of cancers including CRC." (PMID 26968810, 2016).
cancer (continued). "MTA1, master coregulatory biomarker, could be a novel target for cancer therapy, helping to determine the diagnosis and prognosis of tumors." (PMID 26878004, 2016). "Therefore MTA1 is a good target for diagnosis, prognosis, and therapy of human cancers; but more studies are needed to intensively evaluate its role in cancer therapy and its possible clinical use." (PMID 26878004, 2016). "MTA1 has also been shown to stimulate T-cell response in patients with cancer." (PMID 26878004, 2016). "Overexpression of MTA1 in cancer cells enhances cancer cell growth." (PMID 25644400, 2015). "Expression of MTA1 correlates well with the metastasis potential of human cancers." (PMID 25885317, 2015). "MTA1 is known to promote the invasion and migration in a variety of cancer." (PMID 26698569, 2015). "This line of evidence indicates that MTA1 may become a new marker for predicting cancer metastasis, or even cancer outcome." (PMID 24396455, 2014). "In addition to breast cancer, MTA1 was also proved to be closely correlated with aggressiveness in most types of human cancers." (PMID 24970816, 2014). "The present study aimed to explore the potential role and mechanism of MTA1 in cancer." (PMID 24970816, 2014). "The differentiation level decreased with increasing nuclear MTA1 expression according to the mean rank, indicating that nuclear MTA1 may inhibit cancer cell differentiation." (PMID 24970816, 2014). "We evaluated the effects of the MTA1 gene on the adhesion ability of cancer cells." (PMID 24396455, 2014). "Thus, it is important to explore other possible mechanisms by which MTA1 promotes cancer progression." (PMID 24970816, 2014). "MTA1, the first gene identified in this family, has been repeatedly reported to be overexpressed along with its protein product, MTA1, in a wide range of human cancers." (PMID 25009653, 2014). "Herein, we determined whether cytoplasmic MTA1 is also involved in cancer promotion and attempted to characterize the difference between nuclear and cytoplasmic MTA1 functions." (PMID 24970816, 2014). "Recent studies have revealed that MTA1 is important in regulating cancer behaviors." (PMID 24396455, 2014). "In conclusion, the expression of HDAC1 and MTA1 may be required to promote the development of neoplastic transformation in cancer cells with squamous and adeno differentiation." (PMID 25009653, 2014). "The expression of HDAC1 and MTA1 may be involved in duodenoesophageal reflux-induced neoplastic transformation of the esophageal mucosa into cancer cells with squamous and adeno differentiation." (PMID 25009653, 2014). "RNAi against MTA1 significantly decreased the malignant phenotypes of cancer cells." (PMID 24396455, 2014). "Whether MTA1 regulates the metastasis of cancer cells through microtubules should be further investigated." (PMID 24970816, 2014). "Moreover, our data showed involvement of MTA1-mediated signaling in cancer cell growth and metastasis." (PMID 23469203, 2013). "Experimental studies have shown that MTA1 may play an important role in carcinogenesis and cancer progression, including malignant transformation, angiogenesis, invasion and metastasis, by interacting with various cell signaling pathways." (PMID 22537306, 2012).